APOE (apolipoprotein E)
Diseases named in the same sentence as APOE in open-access papers (continued):
Sharing a sentence is not in itself a finding about the gene and the disease.
Cognitive impairment (continued). "Youn and colleagues investigated the association between APOE ε7 expression and cognitive impairment, with the results suggesting that ε7 could serve as a risk factor for cognitive impairment and is particularly associated with vascular disease." (PMID 30866553, 2019). "Second, the APOE antagonistic pleiotropy hypothesis proposes that the APOE ε4 allele is linked to better cognitive functioning in young adulthood and then it reverses to confer cognitive deficits in older age." (PMID 30863302, 2019). "In addition, other factors such as brain metabolism and vascular reactivity seem to be associated with an APOE genotype, which predisposes to cognitive impairment later in life." (PMID 30677746, 2019). "Data from apoE KO mice indicate that these mice have age-dependent synaptic loss and cognitive deficits, however these data could be confounded by the peripheral hyperlipidemia that results from loss of apoE systemically." (PMID 31052389, 2019). "As apolipoprotein-E also associated with serum lipids transport, it may have impact on relationships between serum lipid parameters and cognitive impairment." (PMID 30611281, 2019). "One mechanism by which ApoE loss could lead to cognitive impairment is its effect on the vasculature." (PMID 29510495, 2018). "Several results have showed ApoE deficient mice with cognitive impairments." (PMID 29510495, 2018). "Additional experimental studies are required to test the hypothesis that ApoE genotype modifies the risk for cognitive impairment in aging subjects with T2DM." (PMID 29896424, 2018). "Although a larger cohort study has not supported the APOE ε4 allele as a risk factor for depression as a prodrome in AD, another study has found an interaction between APOE ε4 genotype and depression, as well as a higher risk of incident mild cognitive impairment in male depressed patients." (PMID 29997470, 2018). "Moreover, as expected, the APOE-ε4 allele, a high level of dependence, and cognitive disorders were associated with AD in our population (p = 0.0071, p < 10−4, and p < 10−4, respectively)." (PMID 30044434, 2018). "Association of cognitive impairment with HSV1-seropositive APOE-ε4 in aged cardiovascular patients." (PMID 30405395, 2018). "Interestingly, there was a notable increase in plasma hcy level and significant decrease in serum BDNF level in amnestic mild cognitive impairment patients that converts to AD patients, especially in those with the APOE ε4 allele." (PMID 30172984, 2018). "Chemotherapy induced cognitive impairment may also be associated with genetic vulnerability factors: the genes coding apolipoprotein E (APOE) and catechol-O-methyltransferase (COMT) have been suggested to be variables." (PMID 29113386, 2017). "As this study was conducted as a pilot study, the small sample size may not reflect the true associations between α-synuclein levels, ApoE genotypes and cognitive impairment in PD." (PMID 29326545, 2017). "These alterations may render APOE ε4 carriers more susceptible to AD-related pathology and predict conversion to AD in individuals with mild cognitive impairment (MCI)." (PMID 28137305, 2017). "However, 50% of the ε4 carriers in Riese and colleagues’ study had amnestic mild cognitive impairment, which makes it difficult to disassociate the effects of APOE from any interaction between APOE and underlying amyloid pathology." (PMID 28323160, 2017). "In the present study, we tested the hypothesis that female ApoE4 and ApoE-deficient mice are vulnerable for high-fat diet induced neurodegeneration and cognitive impairment." (PMID 27171180, 2016). "Regulatory and IRB issues were related to absence of language regarding the potential risks, consent for the use of SELECT specimens for the genetic screening of ApoE alleles, and the re-consent process for participants who met the criteria for cognitive impairment." (PMID 27519183, 2016).
Cognitive impairment (continued). "ApoE-deficient and human ApoE4-knockin mice have shown cognitive impairment and vascular changes." (PMID 27171180, 2016). "Collectively these data support the observation that postsynaptic proteins are affected prior to presynaptic proteins and this effect may underlie apoE-modulated cognitive deficits." (PMID 25871877, 2015). "A further open issue is the possibility that smaller hippocampal volumes might be compensated by increases in activity, which has previously been found in patients with mild cognitive impairment or in cognitively intact carriers of the APOE-ε4 allele." (PMID 23269366, 2014). "The aim of this work was to investigate the cognitive and neural (functional) effects of the APOE e4 allele during mid-age (45–55 years), where a transition toward cognitive deficit might be expected." (PMID 24582638, 2014). "So decreased ApoE levels would lead to synaptic zinc deficiency and cognitive impairments." (PMID 24971061, 2014). "Although the APOE-ε2 allele has been associated with protection from morbidity, results from the Rotterdam Study indicate that this effect is clearest for the ε2ε3 genotype, with a greater risk of cognitive impairment for the ε2ε4 genotype." (PMID 24795624, 2014). "However, they can be studied in aging macaques, who are all APOE-ε4 homozygotes and naturally develop cognitive deficits, calcium dysregulation, synapse loss, tau and amyloid pathology and autophagic degeneration, including elevated plasma pT217Tau, a new blood biomarker of incipient AD." (PMID 40735190, 2025). "A clinical trial was conducted to assess the cognitive impacts of DHA‐rich fish oil intake in older subjects with mild cognitive impairment, and to explore whether the apolipoprotein E (APOE) ɛ4 allele modulates outcomes related to cognition and psychological well‐being." (PMID 40918179, 2025). "Furthermore, the apolipoprotein E (APOE) ε2 allele is associated with a higher WMH volume, and individuals carrying the APOE ε2 allele may have more severe cognitive impairment." (PMID 40470487, 2025). "Moreover, few studies have evaluated how various dimensions of PA might interact with APOE ε4 genotype to affect cognitive impairment risk." (PMID 39789564, 2025). "In conclusion, our analysis from a large population‐based study highlights blood apoE4 levels as a potentially modifiable risk factor for cognitive impairment and could support the development of novel strategies that target individuals who carry the APOE ε4 risk gene for AD." (PMID 39234633, 2024). "Pathological mechanisms linking IR to cognitive impairment include dysregulation of the insulin signaling pathway affecting hippocampal plasticity, amyloid precursor protein metabolism, tau protein deposition, neuroinflammation, and apolipoprotein E ε4 allele expression." (PMID 38622624, 2024). "It remains unclear whether the level of blood apoE confers risk for cognitive impairment or AD." (PMID 39234633, 2024). "Similarly, genes such as apolipoprotein E (APOE) are strongly associated with cognitive impairment and could have confounded the studied associations." (PMID 38890509, 2024). "The ApoE rs7412, rs7259620 and rs405509 loci were associated with cognitive impairment in the elderly population, and there was an interaction between plasma metalloid Cd and the rs7259620 and rs405509 loci that increased the risk of cognitive impairment in the elderly population." (PMID 37644506, 2023). "Also, including subjects with mild cognitive impairment (MCI) in LD analyses as a separate stratum may help to identify APOE allele-dependent genetic factors contributing to MCI progression to AD." (PMID 35809216, 2023). "Furthermore, the imbalance in the ApoE isoforms could explain the pathophysiological process of cognitive impairment linked to sporadic AD." (PMID 38132357, 2023). "However, the mechanism of how APOE ε4 and hypertension lead to the increased risk of cognitive impairments remains unclear." (PMID 35624902, 2022).
Cognitive impairment (continued). "Moreover, ApoE polymorphism, particularly the ApoE-ε4, which derives from rs429358 and rs7412 polymorphism, represents a genetic predisposing factor for developing AD and cognitive impairment." (PMID 35351068, 2022). "In addition, patients with cognitive impairment were more likely to carry the APOE ε4 allele." (PMID 35550625, 2022). "In APOE ε4/4 carriers, CMBs, cortical superficial siderosis, white matter hyperintensities, and enlarged perivascular spaces were associated with lower levels of CSF amyloid β (Aβ) 42 in the whole cohort, and in individuals with AD and mild cognitive impairment (p < 0.05)." (PMID 35912087, 2022). "Finally, we investigated whether variations in ApoE and Tau phosphorylation might cause cognitive impairment in P6 and P60 animals." (PMID 35810473, 2022). "In addition, the ApoE gene polymorphisms were also associated with cognitive impairment." (PMID 34135129, 2021). "Therefore, we conducted this study to explore the relationship between cognitive impairment and ApoA1 and ApoB levels in patients with schizophrenia, because it may be altered by the ApoE polymorphism rs429358." (PMID 34135129, 2021). "A recent single case publication showing that a patient with a presenilin 1 mutation was resistant to cognitive impairment, likely due to a homozygous mutation in APOE, supports the hypothesis that APOE might play an important role in this tau pathology acceleration." (PMID 31866851, 2019). "In addition, we hypothesized that the gene–brain–cognition model may potentially be able to elucidate the mechanisms underlying APOE-associated cognitive impairment in the MCI group." (PMID 32226373, 2019). "Moreover, it was early proposed that ApoE−/− mice have highly increased plasma lipid levels, which may independently cause synaptic dysfunction and cognitive deficits." (PMID 30577526, 2018). "Accordingly, recent studies have shown that genetic factors may be linked to cognitive impairments in cancer patients after therapy; for example, the gene encoding apolipoprotein E (APOE), located in chromosome 19, which functions in lipid transport and regulation of inflammation." (PMID 28377717, 2017). "Interestingly, genetic risk score based on the accumulation of multiple risk alleles in BDNF, COMT and APOE for AD combining multiple genetic influences may be more useful in predicting late-life cognitive impairment than individual polymorphisms." (PMID 28443016, 2017). "However, the potential mechanisms underlying the relationships among depression, APOE genotype, and mild cognitive impairment remain largely unknown." (PMID 27406263, 2016). "Furthermore, inflammation-mediated damage in the apolipoprotein E (ApoE) allele 4 suggests a plausible marker for cognitive impairment, possibly due to increased viral replication, which could eventually lead to AD." (PMID 27931194, 2016). "We created a genetic risk score to represent the accumulation of risk genotypes of polymorphisms in BDNF, COMT, and APOE to test whether the risk score predicted the presence of late-life cognitive impairment above and beyond that of each individual gene polymorphism." (PMID 26366299, 2015). "Predictions of cognitive impairment were more robust when blood markers were combined with clinical indicators for AD (age, sex, body mass index, years of education, and APOE ε4 carrier status)." (PMID 40138103, 2025). "This study investigated the relationship between TL and the APOE genotype in individuals with cognitive impairments (CIs)." (PMID 40429722, 2025). "Our study used a naturally aged apoE-target replacement homozygous mice model to reveal that aged male apoE4-TR mice developed cognitive impairment earlier than female apoE4-TR mice." (PMID 39833961, 2025). "The objective of this study was to analyze the relationship between cognitive impairment (CI), unhealthy weight, and APOE genotype status in individuals of predominantly African descent." (PMID 41439935, 2025).
Cognitive impairment (continued). "Recent research has demonstrated that ApoE−/− mice fed an HFHCD to establish an AS model develop cognitive impairments." (PMID 40556958, 2025). "They reported independent effects of Aβ abnormality and APOE genotype on cortical thinning and cognitive impairment in late MCI and AD patients." (PMID 40167963, 2025). "A significant interaction between high FSH and APOE ε4 carrier status on cognitive impairment was observed (p < 0.05)." (PMID 41180813, 2025). "Research76has also confirmed that the interaction between APOE and the pathological deposition of Aβ is an important mechanism by which APOE affects cognitive impairment, such as in AD, DCI, and VD." (PMID 39814004, 2025). "According to the GSEA phenotype analysis, APOE, BDNF, CACNA1A, COMT and UCHL1 were identified as the main genes associated with cognitive impairment (FDR q-value < 0.05)." (PMID 41301762, 2025). "This study investigated associations between late-life PA levels, midlife-to-late-life activity patterns, and cognitive impairment in Chinese older adults, considering potential moderation by apolipoprotein E (APOE) ε4 genotype." (PMID 39789564, 2025). "AD is characterized by significant myelin breakdown, driven by the ε4 allele of a lipid transporter apolipoprotein E (APOE4), which contributes to the disruption of neuronal communication and cognitive deficits." (PMID 40429767, 2025). "This sex-specific effect remained statistically significant among controls and mild cognitive impairment patients when the analysis was restricted to APOE ε3/ε3 and APOE ε3/ε4 genotypes." (PMID 41409615, 2025). "Stratified analyses were performed based on sex, age, degree of cognitive impairment, APOE genotype and brain Aβ burden." (PMID 40717521, 2025). "Our study also highlighted an interaction between FSH and APOE ε4 in cognitive impairment: in APOE ε4 carriers, the adverse effect of high FSH on cognition was more pronounced, partially consistent with the results from animal studies." (PMID 41180813, 2025). "The associations with anxiety, delusions, and hallucination were the strongest and showed the least mediation by cognitive impairment severity, pointing to a more direct role of APOE in these symptoms." (PMID 39974048, 2025). "This study enhances our understanding of the relationships between PA profiles, APOE ε4 genotype, and cognitive impairment in Chinese older adults." (PMID 39789564, 2025). "Although the relationship between APOE and chemotherapy remains poorly investigated, there is substantive evidence linking APOE to cognitive impairment in patients undergoing chemotherapy." (PMID 41390817, 2025). "The apolipoprotein E (ApoE) genotype is a well-established genetic determinant of cognitive impairment." (PMID 40349252, 2025). "A novel finding in our study was that each additional copy of APOE E4 conferred between 11% and 35% increase in the odds of reporting hallucinations and cognitive impairment in PD." (PMID 40926580, 2025). "This study aims to investigate the early dynamic expression of ApoE after TBI and its association with oxidative stress and cognitive impairment, thereby providing a clinical basis and research foundation for its potential role in TBI repair mechanisms." (PMID 41394006, 2025). "APOE on 19q13.32, APOC4-APOC2 on 19q13.32, and TOMM40 on 19q13.32 were previously shown to be associated with AD and cognitive impairment." (PMID 39975850, 2025). "In this regard, in a supplementary analysis, after the use of 3.3 in the IQCODE as a cut-off point for determining incident cognitive impairment instead of 3.6, the interaction between MBI psychosis and APOE allele status became insignificant." (PMID 38473892, 2024). "Single genetic brain–behavior interactions involving GSK3β polymorphisms, apolipoprotein E (APOE) ε4 allele, COMTVal158Met, and ACE D allele were observed in mild cognitive impairment (MCI) and AD patients." (PMID 39324544, 2024).
Cognitive impairment (continued). "As behavioral results show gender-related differences, with ApoE KO female mice displaying greater cognitive impairment, only females were employed here to avoid confounding factors." (PMID 38891031, 2024). "Further analysis was conducted to explore the contributions of CSF α-synuclein and inflammatory factors to tau pathology and cognitive impairment, utilizing mediation models and adjusting for age, gender, education, and APOE ε4 genotype." (PMID 38725083, 2024). "The keywords were DNA methylation, gene expression, cognitive impairment, apolipoprotein E and pathology." (PMID 38292341, 2024). "The identification of broader cognitive deficits, particularly in females with APOE ε4, highlights the need for targeted assessment and intervention strategies." (PMID 39886338, 2024). "Subsequently, a multivariate logistic regression analysis was employed to investigate the link between cognitive deficits and APOE ε4, along with lifestyle patterns." (PMID 39639910, 2024). "Most importantly, genetically, the apolipoprotein E (apoE) 4 gene is involved in the development of cognitive impairment by regulating interferon-related gene expression in the choroid plexus." (PMID 38850523, 2024). "Nevertheless, this interaction between oxysterols and APOE in relation to cognitive impairment should be interpreted with caution given the small number of cases among APOE2+ carriers." (PMID 38574442, 2024). "The notion that females are more vulnerable to cognitive impairment in the presence of the APOE ε4 genotype has been supported by studies indicating that sex differences can significantly modulate the cognitive effects of genetic risk factors." (PMID 39886338, 2024). "Marked cognitive impairments often manifest at approximately 50 years old in autosomal dominant Alzheimer’s disease, 75 years old in APOE ε4-related sporadic Alzheimer’s disease, and 85 years old in APOE ε4-unrelated sporadic Alzheimer’s disease." (PMID 37239094, 2023). "This suggests a modifying relationship of ApoE on CP enlargement with progression of cognitive impairment." (PMID 36970283, 2023). "It has been shown to reduce APOE-4-induced cognitive impairment in an Aβ plaque load-independent manner." (PMID 36981618, 2023). "In a series of models based on model 1, we evaluated the association of different sleep parameters, sex, race and ethnicity, years of education, and APOE*E4 status with the incidence of cognitive impairment with age." (PMID 38048131, 2023). "The differences in gene frequencies and genotype frequencies of the ApoE rs7412 and rs7259620 genotype frequencies were statistically different between the cognitive impairment group and the control group (P < 0.05)." (PMID 37644506, 2023). "We observed that possession of one (HR = 1.25, 95% CI [1.16–1.35], P<0.001) or two copies (HR = 1.68, 95% CI [1.36–2.09], P<0.001) of APOE-ε4 resulted in significantly greater hazard for developing cognitive impairment in later life (Model S1.1)." (PMID 38048316, 2023). "Compared to people with the APOE 3/3 gene, carriers of the APOE 3/4 gene show significantly more cognitive impairments related to working memory, visuospatial memory, and executive function 2.5 and 5 h after administration of lorazepam." (PMID 37781704, 2023). "Then, compared to the APOE ε3/ε3-carriers, the APOE ε4-carriers showed earlier onset of cognitive impairment in AD." (PMID 38132357, 2023). "Camarda's study assessed WM hyperintensities using the APOE genotype and normal cognition, mild cognitive impairment and AD brain imaging studies, and the visual scoring scale." (PMID 37304017, 2023). "In summary, our results reveal that ApoE ε4 genotype was associated with cognitive dificits in Chinese Han T2DM patients, and GSK‐3β plays a mediative role between ApoE ε4 and cognitive impairment." (PMID 37700547, 2023). "Lastly, using Baron and Kenny modeling, we unveiled a mediative role of GSK‐3β activity between ApoE ε4 and cognitive impairment." (PMID 37700547, 2023).